CXCR4 (C-X-C motif chemokine receptor 4)
Diseases named in the same sentence as CXCR4 in open-access papers (continued):
Sharing a sentence is not in itself a finding about the gene and the disease.
tumor (continued). "Cancer stem cells, which are believed to represent a drug-resistant cell population that can survive even chemotherapy, overexpress CXCR4, which correlates with tumour aggressiveness and metastatic potential." (PMID 36140541, 2022). "Studies in recent years have confirmed the close link between SDF-1/CXCR4 axis and tumor cell proliferation, infiltration, and directional migration." (PMID 35545781, 2022). "Research has focused on the development of CXCR4 antagonists, mainly small molecules, peptides, and antibodies, that can act directly on tumor cells or by regulating the tumor microenvironment." (PMID 35456719, 2022). "Overall, our findings provide further mechanistic support for prior in vitro and in vivo studies demonstrating synergistic anti-tumor effects with combined CXCR4 and PD-1 antagonism." (PMID 35797269, 2022). "CXCR4 also enhanced migration of NK cells to bone marrow as a means of targeting bone-marrow-resident tumor cells such as leukemia." (PMID 35432319, 2022). "As the amount of CXCL12 expression increases, the amount of CXCR4 increases in endothelial cancer cells in the tumor microenvironment and affects the cells forming spheroids." (PMID 36551144, 2022). "As such, further studies are needed to elucidate the role of systemic inflammation detected by CXCR4 PET in those tumor subtypes." (PMID 35674738, 2022). "Last but not least, the cell line BxPC3 used in the study showed moderate expression of both CXCR4 and integrin αvβ3, which accounted for a part of the reason for suboptimal tumor imaging." (PMID 36145541, 2022). "Here, we explored the MIF/CXCR4 pathway in primary NB tumor biopsies and BM-derived disseminated NB tumor cells (DTCs) using publicly available gene expression datasets." (PMID 35715791, 2022). "C-X-C chemokine receptor 4 (CXCR4) is a chemokine receptor that promotes tumor progression and metastasis." (PMID 35269297, 2022). "A variety of chemokines and chemokine receptors are correlated with cancer cell metastasis, and CXCL12/CXCR4 axis is a key representative system, which participates in the metastasis of various tumor cells." (PMID 35770088, 2022). "In this study, we report that CXCR4+ cancer cells were present in the invasive tumor front in an orthotopic mouse model." (PMID 35456719, 2022). "The cooperation between Notch and CXCR4/CXCL12 has been reported in tumor angiogenesis and hematological malignancies." (PMID 36266453, 2022). "In conclusion, PGK1-invovled metabolic reprogramming and activation of CXCR4/ERK signaling pathway contributes to tumor growth and sorafenib resistance of KIRC." (PMID 35121728, 2022). "Compared with [68Ga]Ga-/[177Lu]Lu-PSMA, an already established theranostics agent that attaches to the prostate-specific membrane antigen (PSMA) present on the neovasculature of many tumor types, CXCR4 is present on both the neovasculature and the tumor cells." (PMID 33550492, 2022). "Consistently, our previous work supports the selective biodistribution of the nanotoxins to the high CXCR4-overexpressing tumor tissue, avoiding the accumulation and off-target toxicity in normal organs with low or negligible CXCR4 expression." (PMID 35120582, 2022). "Inhibition of CXCR4 with CQ has also been shown to delay tumor progression in esophageal cancer in mice." (PMID 36559044, 2022). "CXCR4 is essential for metastatic spread to organs and thereby allows tumor cells to access cellular niches, such as the bone marrow, that favor tumor-cell survival and growth." (PMID 35159023, 2022). "High CXCR4 expression in tumor cells promotes invasiveness and metastasis, which is exacerbated by high CXCL12 expression in lymph nodes but can be prevented by inhibiting the receptor." (PMID 36164329, 2022). "Our work provides a possible mechanism by which prior studies have demonstrated that combined CXCR4 and PD-1 inhibition leads to decreased tumor growth." (PMID 35797269, 2022).
tumor (continued). "Secondly, we developed a CXCR4+ SC EC model to evaluate the percent of the administered dose that reaches the tumor tissue, since the subcutaneous tumor model is more suited than the orthotopic model for this specific purpose." (PMID 35884987, 2022). "Chemokine receptor 4 (CXCR4) is overexpressed in numerous tumor types, and plays a critical role in tumor growth and invasiveness, as well as metastasis." (PMID 35223907, 2022). "For example, MIF is reported to activate MAPK and its downstream signals via binding to CXCR4 on MSCs, inducing tumor homing of MSCs." (PMID 35842634, 2022). "We developed a CXCR4+ subcutaneous model, implanting 107 CXCR4+ Luciferase+ AN3CA cells in the flank of Swiss nude mice to validate tumor cells engraftment and growth." (PMID 35884987, 2022). "CXCL-12 receptor 4 (CXCR4) inhibitors can be applied to recruit T cells to accumulate in cancer cells as well as cooperate with α-PD-L1 to significantly reduce the number of tumor cells." (PMID 35681617, 2022). "Several studies have reported the presence of CXCR4 on blood vessels as well as on tumor cells surrounding these vessels." (PMID 33550492, 2022). "The CXCL12/CXCR4 axis mediates the metastasis and homing of immune cells at tumor sites, thus affecting the specific immune response." (PMID 35893797, 2022). "It is thought that CXCR4 can be silenced when in a heterodimeric complex with CB2, which allows for the function of CXCR4 to be inhibited, reducing tumour growth or metastasis." (PMID 35909575, 2022). "Blocking CXCR‐4 with CTCE‐9908 can affect tumour cell metastasis if the blocking is conducted prior to the onset of metastasis." (PMID 36398426, 2022). "The CAM-grown xenografts were histologically characterised, demonstrating vascularisation of the graft, preserved expression of human CXCR4, and viability of the tumour cells within the grafts." (PMID 36428644, 2022). "The remaining 330 cores (163 tumors) showed a large inter- and intra-tumor variation for CXCR4 expression; also seen in the resected tissue of the seven pilot patients—not directly translatable to [68Ga]Ga-Pentixafor PET results." (PMID 33550492, 2022). "Since CXCR4 overexpression in tumor tissue has been related to enhanced migration, metastatic potential, and a higher risk of recurrence in HNSCC, we wanted to evaluate its suitability as a receptor for targeted drug delivery." (PMID 35456719, 2022). "On the contrary, CXCR4 overexpression increased the tumor-derived DNA expression of ERK1/2 and MMP2/9, increased the proliferative and migratory activities of SK-Hep1 cells, and reduced apoptosis." (PMID 35860597, 2022). "Overall, the antibodies against SSTs and CXCR4 produced distinct immunostaining of the plasma membrane but also of the cytoplasm of the tumour cells." (PMID 35799158, 2022). "68Ga-Pentixafor is used to non-invasively image the expression of CXCR4 in tumours and has been widely used in haematological malignancies." (PMID 36140541, 2022). "Another potential solution would be to pre-inject a small amount of CXCR4 antagonist to reduce liver uptake, thus improving tumor uptake." (PMID 36145541, 2022). "In this study, CBFB knockdown decreased tumor burden, bone metastasis, and markers of bone metastasis, including CXCR4, Snail, CD44, OPN, Runx2, and IL-6." (PMID 35903297, 2022). "Previous studies have observed that CXCR4 expression is higher in liver metastases than in primary CRC tumor tissue and suggest that the mechanism of development of liver and lung metastases is different." (PMID 35406582, 2022). "After having visualized CXCR4 expression of tumor lesions in an in vivo setting, patients can be scheduled for CXCR4-directed ERT using the ß-emitting theranostic twin [177Lu]/[90Y]PentixaTher." (PMID 35674738, 2022).
tumor (continued). "g., genotoxic, microtubule inhibitor, toxin...) with high cytotoxic activity in EC in vitro, expecting first to inhibit tumor growth in the CXCR4+ SC EC model, and then, to achieve the control of metastatic dissemination in the CXCR4+ ORT EC model." (PMID 35884987, 2022). "Our previous work demonstrated the selective accumulation of nanoparticles in CXCR4-overexpressing tumor tissues, together with a CXCR4-dependent cytotoxic effect and a potent antitumor effect in vivo." (PMID 35456719, 2022). "Within the tumour microenvironment, the major CXCR4-expressing cells are B lymphocytes and plasmacytoid dendritic cells, both potentially contributing to an immunosuppressive state, which promotes tumour progression." (PMID 36140541, 2022). "Apoptosis of SK-Hep1cells was significantly reduced after treatment with tumor-derived DNA combined with CXCR4 or CCR7 overexpression but increased after treatment with sinocine hydrochloride." (PMID 35860597, 2022). "The multi-functional scaffold generated by c-terminal modification of LY2510924 can be applied to CXCR4-targeted probe development, tumor imaging, and drug-targeted therapy." (PMID 35893797, 2022). "Recently, the use of radiotracers targeting CXCR4 or integrin αvβ3 for tumor imaging has been widely investigated." (PMID 36145541, 2022). "SDF-1 enhances optic glioma cell survival via the CXCR4 receptor, whereas blocking CXCR4 inhibits tumor development in vivo." (PMID 35269652, 2022). "Anti-human CXCR4 or anti-human vimentin antibodies were shown to be specific and highly sensitive markers in tumor cells in our CXCR4+ model." (PMID 35884987, 2022). "CXCR4 affects tumor growth; its overexpression is a driver of a large number of human malignancies and a marker of poor prognosis, especially in patients with breast, prostate, colorectal and lung cancer." (PMID 36293358, 2022). "It was observed that activation of CXCR4 by CXCL12 enforced tumor resistance to therapies by decreasing apoptotic signaling." (PMID 36612163, 2022). "We therefore first investigated neutrophil chemotactic factors and found that tumor‐infiltrating neutrophils expressed higher CXCR4 than that on peritumoral or non‐tumor neutrophils." (PMID 34957697, 2022). "The anti-tumour effects of the anti-PD-L1/CXCR4 nanobody were evaluated in tumour cell-killing assays in vitro and in an in vivo xenograft mouse model of PDAC." (PMID 36284271, 2022). "GSMDE and CXCR4 expression in HNSCC patient tumor samples was also assessed by immunohistochemical staining." (PMID 35120582, 2022). "The NEC913 cells grew as spheroids in suspension culture or embedded in extracellular matrix, recapitulated characteristics of the PDX tumor, and stained positive for CXCR4." (PMID 35454817, 2022). "The CXC chemokine receptor 4 (CXCR4) and integrin αvβ3 play important roles in tumor development, progression, invasion, and metastasis, which are overexpressed in many types of human cancers." (PMID 36145541, 2022). "There is evidence that CXCR4 is expressed in ovarian cancer primary tumours and its ligand CXCL12 is expressed in the ascitic fluid." (PMID 36140541, 2022). "This has been associated with several mechanisms involving mediator-produced CAFs including expression of CXCL12 that mediates T cell exclusion from the tumor and resistance to immunotherapy via CXCR4." (PMID 35977489, 2022). "Deleting CXCR4 in myeloid cells enhanced the anti-tumor immune response, resulting in significantly reduced tumor growth in melanoma." (PMID 35585567, 2022). "CXCL12 and CXCL11 affect tumor cell functions by either binding their prime receptors, CXCR4 and CXCR3, respectively, and/or CXCR7 as a common second chemokine receptor." (PMID 36539774, 2022). "C-X-C motif chemokine ligand 12 (CXCL12) and its receptor C-X-C motif chemokine receptor 4 (CXCR4) have emerged as promising therapeutic approaches targeting tumor growth and metastasis." (PMID 35615089, 2022).
tumor (continued). "Our analysis of the online TCGA database on NSCLC samples shows significant tumor-promoting effects of CXCR4." (PMID 35064116, 2022). "Possibly, other neutrophil-attracting chemokines (such as CXCR4) compensated for the loss of CXCR2 in this experimental setting and attracted pro-angiogenic neutrophils into the tumor tissue." (PMID 35158807, 2022). "This was confirmed in a meta-analysis of 7 studies looking at 1055 patients with OC, which demonstrated that the overexpression of CXCR4 in OC correlates with reduced OS as well as with tumour depth, lymph node involvement and TNM staging." (PMID 36140541, 2022). "PGK1 exhibits pro-tumorigenic properties in vitro and in a xenograft tumor model by accelerating glycolysis and inducing CXCR4-mediated phosphorylation of AKT and ERK." (PMID 35121728, 2022). "CXCR4 is overexpressed in EC tumor tissue, epitomizing an unexploited therapeutic target for this malignancy." (PMID 36612081, 2022). "CXCL12 activates tumor cells and attracts Tregs and MDSCs by binding with its receptor CXCR4 to induce angiogenesis and create an immunosuppressive environment for tumor cell proliferation." (PMID 35083488, 2022). "The CXCL12/CXCR4 axis is crucial signaling for tumor cells cross-talking with the tumor microenvironment that paves a path for tumorigenesis." (PMID 35615089, 2022). "In HNSCC, high expression of SDF‐1/CXCR4 indicates invasive tumor behavior and correlates with local proliferation and lymphatic and distant metastasis." (PMID 34964283, 2022). "And the CXCL12/CXCR4 axis in PDA is a promoter of tumor proliferation, invasion and chemoresistance." (PMID 36131941, 2022). "Next, we demonstrated that repeated doses of T22-PE24-H6 inhibit tumor growth in a subcutaneous CXCR4+ CRC model, also through pyroptotic activation." (PMID 35532120, 2022). "A few researchers detected CXCR4 expression in tumor cells and tumor-infiltrating lymphocytes but scarcely in normal lung tissues." (PMID 35729596, 2022). "Blocking CXCR4 in the signal cascade leads to a reduction in tumor endothelium with a mechanism that is VEGF-independent." (PMID 36432658, 2022). "The purpose of this study was to further optimize BL02, notably with the aim of improving the tumour-to-kidney contrast ratios for the eventual development of a CXCR4 therapeutic radioligand." (PMID 35890397, 2022). "The hypoxic tumor microenvironment can favor the upregulation of CXCR4 and CXCL12 in several cell types such as endothelial cells and cancer cells through mobilization of the hypoxia induced factor 1 (HIF-1α)." (PMID 35406582, 2022). "The Kaplan Meier survival curves showed that the pCXCR4/CXCR4 tumor infiltrating immune cells in primary cancer biopsies have a tendential positive effect on RFS, nevertheless this was not significant (p = 0.126)." (PMID 35397601, 2022). "Other studies demonstrated that SDF‐1/CXCR4 was responsible for postirradiation tumor revascularization in glioblastoma." (PMID 36254250, 2022). "Blockade of CXCR4 is thought to inhibit all the steps necessary for the development of metastatic foci: not only tumour cell infiltration into CXCL12-producing predestination organs, but also adhesion, migration, invasion and tumour angiogenesis." (PMID 36140541, 2022). "Tumor-derived SDF-1 is upregulated in platelets of RM1 tumor-bearing mice and increased circulating SDF-1 is associated with enhanced homing of CXCR4-positive bone marrow-derived progenitor cells to tumors driving angiogenesis." (PMID 35515124, 2022). "(2022) identified a CXCR4+ neutrophil population enriched in metastatic tissue which was functionally expected to enhance tumor invasion." (PMID 35757757, 2022). "The results showed that tumor-derived DNA promoted SK-Hep1 cell invasion, while CXCR4 knockdown reduced SK-Hep1 cell invasion induced by tumor-derived DNA." (PMID 35860597, 2022).
tumor (continued). "We compared the expression of EGFR and CXCR4 in serum sEV with that in the primary tumor tissue assessed by IHC, which is a clinically used gold standard to examine the expression of marker proteins." (PMID 35269297, 2022). "Studies have shown that CXCR4 homodimers have been detected in tumour cells, not only in the cytoplasm but also on the surface of the cell membrane." (PMID 35909575, 2022). "The CXCL12/CXCR4 axis can induce the proliferation of tumor cells via activation of the ERK and AKT signaling pathways." (PMID 35893797, 2022). "In pancreatic ductal adenocarcinoma (PDAC), the CXCL12/CXCR4 axis mediates the desmoplastic reaction; this changes the tumor mechanical microenvironment and promotes drug resistance." (PMID 35893797, 2022). "Tumor samples expressed VECF-C, -D and -R3, as well as CXCL12, CCL21 and CXCR4 with the highest lymphatic vessel density at the invasive tumor edges." (PMID 35163401, 2022). "Several studies have described the potential utility of receptors from the CXC family as biomarkers of response and prognosis in CRC, and CXCR4 expression clearly seems to be a valuable predictor for tumor recurrence in gastrointestinal tumors." (PMID 35397601, 2022). "Inhibition of corresponding receptor CXCR4 in combination with PD-L1 immune checkpoint blockade synergistically impedes tumor growth." (PMID 36230914, 2022). "In contrast, the novel ORT CXCR4+ EC model developed here ensures a correct implantation of cancer cells in the endometrium, avoiding their leakage, while maintaining the tumor microenvironment where EC develops." (PMID 35884987, 2022). "The interaction between CXC chemokine ligand 12/chemokine stromal cell-derived factor-1 (CXCL12/SDF-1) and the corresponding receptor CXCR4 promotes tumor metastasis." (PMID 35630915, 2022). "It has been observed that luteolin acts on tumor-associated macrophage (TAM) and other associated immune cells which releases chemokines, e.g., C-X-C chemokine receptor type 4 (CXCR4, a growth factor involved in the metastasis of cancer." (PMID 36358791, 2022). "CXCL12 interacts also with the CXCR4 present on the surface of mature B cells and mediates the recruitment of B regulatory cells to the tumor site inhibiting T cell activity." (PMID 35565443, 2022). "CXCR4 has been linked to HIV, as well as many different types of cancers due to its ability to stimulate angiogenesis, tumour growth, metastasis and tumour survival, making it an important drug target." (PMID 35909575, 2022). "Given the established role of the HIF-1/CXCL12/CXCR4 pathway in tumor vasculogenesis, antagonists to this pathway are predicted to display clinical potency as anti-vasculogenic agents." (PMID 36568151, 2022). "In fact, a frequent characteristic of tumor cells is the concomitant overexpression of CXCR4/ACKR3 and growth factor receptors (GFR), an important element in cell proliferation and survival." (PMID 36233192, 2022). "Five (71%) of the seven patients showed low to moderate tracer uptake, which did not fully correspond with CXCR4 IHC where all patients showed large intra-tumour variation for CXCR4 staining, even within one section." (PMID 36140541, 2022). "We found that the expression levels of EGFR and CXCR4 in serum sEVs correlated well with the IHC staining results of the primary tumor tissue for the four patients." (PMID 35269297, 2022). "SDF1 binds primarily to CXC chemokine receptor 4 (CXCR4), while the CXCL12/CXCR4 axis has a significant role in tumor progression, metastasis, and cancer cachexia." (PMID 35454797, 2022). "The mean tumor volume of mice in the CXCR4-Kd#2/OVCA420 group was reduced at days 15 and 19 compared with the Scramble-Kd/OVCA420 group (*P<0.05)." (PMID 35681259, 2022). "When tumor cells are co-cultured with neutrophils, the expression of many pro-metastatic genes, including chemokine receptors (CXCR4 and CXCR7), MMPs (MMP12 and MMP13), and growth factors (IL-6 and TGF-β), is significantly elevated." (PMID 36612163, 2022).